SIRT1 (sirtuin 1)
Diseases named in the same sentence as SIRT1 in open-access papers (continued):
Sharing a sentence is not in itself a finding about the gene and the disease.
gastric cancer (continued). "SIRT1 can regulate expression of ARHGAP5 and inhibit the migration and invasion of gastric cancer cells." (PMID 36950520, 2023). "Cancer-associated fibroblast-derived exosomal lncDACT3-AS1 inhibits miR-181a-5p to elevate the levels of its target sirtuin 1 (SIRT1), leading to an increase in antioxidant capacity to inhibit ferroptosis in gastric cancer." (PMID 37686142, 2023). "Recently, a study demonstrated that SIRT1, a histone deacetylase that participated in STAT3 deacetylation, was found to be upregulated in advanced gastric cancer." (PMID 33886682, 2021). "USP22 also promoted gastric cancer progression and metastasis through regulating c-Myc/NAMPT/SIRT1-dependent FOXO1 and YAP signaling." (PMID 34753387, 2021). "In miR-1301-3p-inhibited GC cells, further knockdown of SIRT1 could reverse the inhibitory effect of miR-1301-3p knockdown on gastric cancer cell function." (PMID 33987098, 2021). "miR-543 targets and inhibits SIRT1, a class III histone deacetylase, and promotes gastric cancer cell proliferation and cell cycle progression, suggesting that this miRNA plays a role in cell proliferation." (PMID 32380753, 2020). "Overexpression of miR-204 and knock-down of SIRT1 induce an MET phenotype by increasing E-cadherin and decreasing VIMENTIN levels, and inhibit gastric cancer metastasis." (PMID 30761005, 2019). "To determine the correlation between SIRT1 expression and STAT3 activity during gastric cancer development, we performed the Spearman's correlation analysis in all tissues including the NG mucosa, PL, EGC and AGC tissues." (PMID 28061480, 2017). "Predominantly, the SIRT1, STAT3, and pSTAT3 proteins were detected in the nucleus of gastric cancer tissues and rarely in the cytoplasm." (PMID 28061480, 2017). "Previous studies showed that miR-204 suppressed gastric cancer through targeting USP47, RAB22A, SIRT1, Snai1, and so forth." (PMID 28133610, 2017). "Mechanism researches suggested that SIRT1 can counteract the activation of STAT3 and NF-κB to repress cell growth and lead to G1-phase arrest via NF-κB/Cyclin D1 signaling in gastric cancer." (PMID 29088792, 2017). "Our study was the first to investigate the collaborating effects of SIRT1 and STAT3 in gastric cancer patients." (PMID 28061480, 2017). "In vitro study further confirmed the regulatory effects of SIRT1 in EMT and invasion capability of gastric cancer cells." (PMID 26910278, 2016). "Similar to that of HULC, silent mating type information regulation 1 (SIRT1), a class III histone deacetylase, is also upregulated in tumor tissues and correlates with advanced lymph node metastasis in gastric cancer." (PMID 26910278, 2016). "Luciferase reporter assay was able to confirm SIRT1 to be the direct target of miR-204 and overexpression of miR-204 elevated LKB1 expression and increased anoikis sensitivity in gastric cancer cells." (PMID 26587543, 2015). "All gastric cancer cell lines except for NUGC-4 and STKM-1 cells expressed high levels of SIRT1 protein, and SIRT2 expression levels were low in all cell lines except for MKN-45 cells." (PMID 25033286, 2014). "Therefore, SIRT1 may be the target of miR-204 in gastric cancer cells." (PMID 23768087, 2013). "Additionally, Sirt1 downregulation and Sirt6 upregulation were detected in the presence of MDM2 in gastric cancer cells." (PMID 38254877, 2024). "Sirt6- and Sirt1-mediated gastric cancer cell death via ROS regulation was demonstrated previously in many types of cancer but not in gastric cancer." (PMID 38254877, 2024). "Notably, IGF2BP2 has been found to target SIRT1, ZEB1, and HMGA1, thereby promoting gastric cancer growth and metastasis." (PMID 37865637, 2023). "In the present study, we show that zyxin upregulates SIRT1, which inhibit EMT in gastric cancer." (PMID 37667739, 2023).
gastric cancer (continued). "Moreover, miR-132 has been reported to regulate the SIRT1/CREB/ABCG2 signaling pathway, contributing to cisplatin resistance and serving as a novel therapeutic target against gastric cancer." (PMID 35336739, 2022). "Li and colleagues in their study at gastric cancer (GC) have demonstrated that miR-543 enhances ability to cell proliferation and formation of colony, what in consequence lead to a progression to the S phase, by directly targeting histone deacetylase sirtuin 1 (SIRT1)." (PMID 33413466, 2021). "However, previous data from our lab demonstrated that overexpression of CacyBP/SIP inhibits the growth of renal carcinoma cells and gastric cancer cells, suggesting that CacyBP/SIP has tumor-specific roles, similar to SIRT1, NF-κB, and TGF-beta." (PMID 28196083, 2017). "Also, as expected, the expression levels of SIRT1 and STAT3 mRNA were significantly higher in gastric cancer tissues than in matched normal mucosa from public datasets." (PMID 28061480, 2017). "Our results revealed upregulated expression of SIRT1 in all stages of gastric cancer compared with noncancerous gastric mucosa, suggesting that high SIRT1 levels are likely involved in establishing gastric neoplasticity." (PMID 28061480, 2017). "Moreover, co-ordinated high expression of SIRT1 and STAT3 predicted poor overall survival for advanced gastric cancer patients." (PMID 28061480, 2017). "Our data showed significant upregulation of SIRT1 in all the three gastric cancer stages (PL, EGC and AGC) in comparison to non-cancerous gastric tissue." (PMID 28061480, 2017). "SIRT1, a class III histone deacetylase, is upregulated in lymph node metastases of gastric cancer." (PMID 27438705, 2016). "The findings on DBC1, H4K16Ac, and H3K9Ac also suggested that SIRT1 acted as an oncogene and thus might be a potential target for HDAC inhibitor treatment in gastric cancer patients." (PMID 25146318, 2014). "MKN-45 cells exhibited SIRT1 gene expression that was about 2.5 fold higher than that in fibroblasts, but other gastric cancer cell lines did not." (PMID 25033286, 2014). "And it was also indicated that SIRT1 acts as an oncogene by the results of DBC1, H4K16Ac, and H3K9Ac and might be a target molecule of HDAC inhibitor treatment for gastric cancer patients." (PMID 25146318, 2014). "This study is the first report that high levels of ATF4, commonly seen in tumor cells under stressful circumstances, confers gastric cancer cells with a MDR phenotype, and it identifies that this effect is mediated partly by transactivation of SIRT1 expression." (PMID 22363646, 2012). "We were curious to determine whether SIRT1, which is a stress-related gene critical to MDR development, could be the downstream target of ATF4 responsible for mediating ATF4-induced MDR in gastric cancer cells." (PMID 22363646, 2012). "Furthermore, lower SIRT1 expression levels were observed to be significantly correlated with disease‐specific survival (DSS) in gastric cancer (p = 0.045, HR = 0.63), but there was no notable disparity detected in cases of colon and rectal malignancies." (PMID 41020376, 2025). "Although gender itself did not significantly affect SIRT1 expression, gastric cancer patients showed higher levels in men than in women, which may be related to the higher incidence of gastrointestinal tumors in males." (PMID 41020376, 2025).
gastric cancer (continued). "Therefore, it is feasible that miR-204-5p acts as an anoikis-promoting miRNA by regulating CXCR4, OCT1, etcetera, rather than SIRT1, in gastric cancer." (PMID 33435156, 2021). "Although STAT3 may not be the direct target of SIRT1 in gastric cancer, combinatorial high expression of both these proteins can predict the worst survival outcome." (PMID 28061480, 2017). "Among patients with gastric cancer (GC), there was no statistically significant variation in the plasma SIRT1 levels according to age, the presence of distant metastases from the tumor, or the presence of lymph node metastases." (PMID 41020376, 2025). "In gastric cancer (GC), exosomal DACT3-AS1 derived from CAFs inhibited cell proliferation, migration, and invasion by targeting miR-181a-5p/sirtuin 1 (SIRT1) axis, and increased the sensitivity of GC cells to chemotherapy drugs through the SIRT1-mediated ferroptosis." (PMID 38302430, 2024). "Therefore, we hypothesized that STAT3 may not be a direct target of SIRT1 in our cohort of gastric cancer patients." (PMID 28061480, 2017). "In gastric carcinoma, only the nuclear expression of SIRT predicted poor prognosis of patients but not in cytoplasmic expression of SIRT1." (PMID 24019980, 2013). "Next, we examined SIRT1, ATF4, MDR1, MRP, Bcl-2, and Bax expression levels after 24 hours' incubation with or without the indicated doses of EX-527 in the gastric cancer cells used above." (PMID 22363646, 2012).
myocardial infarction (107 papers, 2012 to 2025). Gross necrosis of the myocardium, as a result of interruption of the blood supply to the area, as in coronary thrombosis. "Within the myocardial tissue, ischemia/reperfusion (I/R) diminished SIRT1 protein and mRNA expression, while the size of myocardial infarction/the ischemic area at risk (AAR) was significantly greater in cardiac-specific Sirt1−/− mice than in control mice." (PMID 40507709, 2025). "Experimental and preclinical studies have indicated that SIRT1, as a cardioprotective factor, can be inhibited by stress factors associated with an increased risk of myocardial infarction." (PMID 37630770, 2023). "In previous studies, we have identified a number of genetic variants within SIRT1 gene promoter in patients with acute myocardial infarction (AMI), Parkinson's disease (PD), and ventricular septal defects (VSD)." (PMID 36747995, 2023). "Together, our results further revealed that AMPK and SIRT1 were associated with RSV treatment on MI/RI‐induced myocardial infarction, cardiac dysfunction and oxidative stress." (PMID 35791579, 2022). "SIRT1 single-nucleotide polymorphisms were associated with premature myocardial infarction, which affected the SIRT1 and endothelial nitric oxide synthase protein expression, irrespective of the underlying SIRT1 genotype." (PMID 31143479, 2019). "In primary cardiomyocytes (in post-myocardial infarction), the expression of SIRT1 and Phd3 were reduced, while cleaved caspase-3 and Hif-1 α expression increased." (PMID 41567643, 2025). "Betulin attenuated the cardiac inflammatory response, decreased myocardial infarct size, and enhanced cardiac electrical signaling by modulating the SIRT1/NLRP3/NF-κB signaling pathway." (PMID 39925805, 2025). "In this regard, the role of SIRT1 in the protection against the damage induced by myocardial infarction has been widely demonstrated." (PMID 41302436, 2025). "A significant reduction in Sirt1 and Phd3 expression, along with an increase in Hif-1α and cleaved caspase-3, was observed in a time-dependent manner post-myocardial infarction (MI)." (PMID 40087582, 2025). "Sirt1 effectively reduces cardiomyocyte apoptosis and myocardial infarction size while enhancing cardiac function post-MI, primarily through the Phd3/Hif-1α signaling pathway." (PMID 40087582, 2025). "Specifically, lncRNA KLF3‐AS1 suppresses miR‐138‐5p, leading to SIRT1 upregulation and cardiomyocyte survival after myocardial infarction." (PMID 41445977, 2025). "Attenuates oxidative mitochondrial damage, reduces myocardial infarction size, improves post-ischemic heart function, decreases apoptosis and oxidative stress, enhances SIRT1 signaling." (PMID 39963239, 2025). "Sirt1 plays a crucial pathophysiological role in multiple biological processes including in the cardiovascular system, such as myocardial infarction, arrhythmia, heart failure, myocardial remodeling and myocardial fibrosis." (PMID 40297134, 2025). "Previous studies have shown that elevated NEU1 expression in myocardial infarction tissues leads to inhibition of the SIRT1/PGC-1α pathway, thereby leading to altered mitochondrial function causing cardiac dysfunction." (PMID 40221400, 2025). "For example, the MSC-Exo-derived lncRNA KLF3-AS1 has been revealed to inhibit the pyroptosis of myocardial cells through the miR-138-5p/Sirt1 axis and promote cell repair, thus reducing myocardial infarction area." (PMID 38627703, 2024). "Studies have shown that NAD+ supplementation reduces myocardial infarction size during cardiac ischemia through the longevity protein Sirt1." (PMID 38764052, 2024). "PGC-1a can also independently stimulate Akt activation, as demonstrated by the promotion of the Sirt1/PGC-1α/Akt signaling pathway in cardiomyocytes of myocardial infarction rats after four weeks of running training." (PMID 38531890, 2024).
myocardial infarction (continued). "Melatonin induces cellular autophagy through the Mst1/SIRT1 signaling pathway and regulates mitochondrial integrity and biogenesis, thereby alleviating post-myocardial infarction cardiac remodeling and dysfunction." (PMID 37754811, 2023). "Another study found that Sirt1 was downregulated in myocardial infarction and that Sirt1 overexpression effectively ameliorated myocardial injury caused by myocardial infarction." (PMID 37396588, 2023). "In circumstances such as hypertrophy and myocardial infarction, SIRT1 has been shown to protect cardiomyocytes." (PMID 35897743, 2022). "Myocardial infarction led to a decrease in the protein levels of SIRT1, PGC-1α, and ATP5D in cardiac muscle tissue." (PMID 35915610, 2022). "In order to ascertain that SIRT1 participated in the verapamil-mediated cardioprotective effects in the mice subjected to I/R, we assessed the cardiac function and myocardial infarct size of the mice." (PMID 35281891, 2022). "Emerging studies have identified that Sirt1 is associated with the activation of Nrf2, and both of them play a protective role in ISO-induced myocardial infarction." (PMID 36483733, 2022). "It is also reported that BMSCs can regulate SIRT1, thereby suppressing pyroptosis of myocardial cell and improving myocardial infarction." (PMID 34248837, 2021). "Sirtuin 1 also exerts cardioprotective effects by reducing endoplasmic reticulum stress against myocardial infarction injury." (PMID 34439776, 2021). "The protective effects of ischemic postconditioning and post-myocardial infarction exercise were accomplished by enhancing SIRT1 expression, indicating its potential regulative role in protective post-stroke exercise." (PMID 33664650, 2021). "As such, curcumin protected against myocardial infarction-induced fibrosis via sirtuin-1 activation in mice and cells." (PMID 32024036, 2020). "In our previous study, TPP1 expression was found to be upregulated in SIRT1-overexpressing OMSCs, which significantly enhanced the ability of these cells to survive after injection following myocardial infarction." (PMID 33195247, 2020). "Sirtuin-1 has been shown to play a key role in the protection against myocardial infarction and in the prevention of the senescence of the vasculature in cells." (PMID 32024036, 2020). "Several studies have pointed out that Sirt1 has a cardioprotective effect, and its expression in the heart is down‐regulated by many stress stimuli that collectively drive the pathogenesis of myocardial infarction." (PMID 32961025, 2020). "In fact, 18 disclosed the previously unrecognized role for SUV39H linking SIRT1 trans-repression of myocardial infarction." (PMID 31569621, 2019). "SIRT1 protein levels were markedly increased in myocardial infarction patients compared to that of the control group." (PMID 31143479, 2019). "We induced ischaemia in WT and heart-specific Sirt1 knockout mice and quantified myocardial infarction." (PMID 28504272, 2017). "We present evidence that the histone H3K9 trimethyltransferase SUV39H links SIRT1 trans-repression to myocardial infarction." (PMID 28361889, 2017). "Our data identify a previously unrecognized role for SUV39H linking SIRT1 trans-repression to myocardial infarction." (PMID 28361889, 2017). "WT hearts had significantly reduced myocardial infarction (pale discoloration) than Sirt1 KO hearts, suggesting that Sirt1 is cytoprotective against the stress induced by ATP depletion." (PMID 28504272, 2017). "Collectively, these findings offer compelling evidence that Sirt1 overexpression provides a protective effect in the context of myocardial infarction by reducing infarct size, alleviating cardiac fibrosis, improving overall cardiac function, and suppressing apoptotic pathways in cardiomyocytes." (PMID 40087582, 2025). "Myocardial infarction treatment may target the SIRT1/UCP-2 axis, suggesting the importance of this pathway in CVDs." (PMID 41567643, 2025).